FGFR1 (fibroblast growth factor receptor 1)
Diseases named in the same sentence as FGFR1 in open-access papers (continued):
Sharing a sentence is not in itself a finding about the gene and the disease.
Obesity (28 papers, 2012 to 2026). Accumulation of substantial excess body fat. "For example, FGF21 analogs and agonists of FGFR1/KLB receptor complexes have displayed therapeutic potential in improving obesity and its associated complications." (PMID 39872218, 2024). "Common and rare FGFR1 variants have been implicated in metabolic traits, including waist-to-hip ratio, body mass index (BMI), obesity, type 2 diabetes (T2D), and fasting glucose levels in population-based genetic epidemiology studies." (PMID 38957656, 2024). "In this manuscript, we used growth in ultra-low attachment conditions to develop a novel phenotypic transformation HTS assay using FGF2/FGFR1 signaling as the target-based mechanism to identify chemopreventive agents for obesity-associated epithelial cancers." (PMID 31311976, 2019). "Genetic studies have demonstrated FGFR1 as a novel susceptibility gene in human obesity with increased adipose tissue levels in obese compared to lean subjects." (PMID 24498293, 2014). "Recently, the Fibroblast Growth Factor Receptor 1 (FGFR1) SNP rs7012413*T was found to be associated with obesity in four different cohorts." (PMID 25427253, 2014). "Therefore, the FGF2/FGFR1 signaling axis is a potential chemopreventive target for obesity-associated epithelial cancers." (PMID 31311976, 2019). "Sex-differential disease-related genes include those associated with obesity (PPARG, INSR), cancer (FGFR1, CD22), and immunity (IL6R, IL3RA)." (PMID 40707586, 2025). "In conclusion, evidence from genetic ablation and exogenous treatment in in vitro models ofadipocytes demonstrate, for the first time, that shed Sdc4 from adipocytes during obesity acts as a novel suppressor of lipolysis through the FGF2/FGFR1 axis." (PMID 40180176, 2025). "Our findings provide direct human genetic evidence to support prior studies investigating the beneficial effect of the FGFR1 signaling pathway as a therapeutic target of diabetes and obesity in humans." (PMID 38957656, 2024). "We have previously shown that the gut-to-brain axis involving taurocholate/FGF15 improved glucose tolerance in multiple models of obesity and diabetes, which was dependent on FGFR1 in AGRP-expressing cells." (PMID 36787185, 2023). "The bispecific anti-FGFR1/KLB agonist antibody BFKB8488A designed against it can treat obesity-related metabolic defects by specifically activating the FGFR1/KLB complex." (PMID 36341333, 2022). "This study thus highlighted FGFR1 as a novel obesity gene that influences adipose tissue and the hypothalamus, thereby initiating obesity and modulating appetite, respectively." (PMID 35983184, 2022). "Cardiac FGF21 was expressed and secreted (real time RT-PCR/western blot and ELISA) in an autocrine-paracrine manner, in response to obesity and hypoxia, involving FGFR1-βKlotho components." (PMID 24498293, 2014). "It is important to mention that FGFR1 has been proposed as a potential regulator of adipogenesis and may contribute to obesity by modulating the number of fat cells." (PMID 39109301, 2024). "FGF1 also plays vital roles in lipid metabolism through the FGF1/FGFR1 signaling pathway and may aid in obesity prevention." (PMID 34306666, 2021). "As circulating FGF2 levels correlate with adipose tissue mass in humans, FGF2/FGFR1 signaling could be a potential mechanism in which obesity influences the mammary gland." (PMID 33019728, 2020). "However, the majority of patients with variants in either FGFR1 and KLB exhibit obesity, dyslipidemia, and insulin resistance." (PMID 33210059, 2020). "The activation of adipose tissue by FGF21 through FGFR1 was suggested by genetic deletion of FGFR1 in adipocytes in mice used in the current study, and this tissue- and molecule-specific actions of FGF21 underlies the breadth of its in vivo beneficial effects on treatment of obesity and diabetes a." (PMID 23106963, 2012).
Obesity (continued). "Subsequently, the shed-Sdc4-induced FGF2/FGFR1 activation inhibits adipocyte lipolysis by suppressing HSL phosphorylation, which uncovered a specific mechanism of shed Sdc4 in the development of obesity." (PMID 40180176, 2025). "In these animals, exercise was shown to induce transcriptional activation of FGFR1 and KLB in adipocytes, resulting in increased sensibility to FGF21, and hence attenuating obesity-induced metabolic dysfunction." (PMID 37019912, 2023). "This is in line with previous studies where it was demonstrated that hepatic levels for β-Klotho, FGFR1 and FGFR3 transcripts were significantly increased in patients with obesity." (PMID 33670024, 2021). "In our results, the induction of the mRNA levels of adiponectin, FgfR1, FgfR4 and Egr1 in scWAT of HFDM mice indicates that, in obesity, maqui supplementation increases the sensitivity to FGF21 of scWAT." (PMID 31480627, 2019). "Altered DNA methylation in promoters of transcription factor genes (PPARA, KLF15, NR3C1, RORA and ATF4) known to regulate FGF21 expression and its binding receptors and co-factors (FGFR1, FGFR3 and FGFRL1 and KLB) has been revealed in relation to the elevated levels of circulating FGF21 in obesity." (PMID 33670024, 2021). "The mRNA levels of JMJD3 and KLB were decreased, whereas those of Fgfr1 and Fgfr4 were increased, after feeding a HFD, suggesting that decreased expression of KLB may contribute to FGF21 resistance in obesity." (PMID 32042044, 2020). "In addition, adipose tissue FGFR1 mRNA and protein levels were elevated in obese subjects and Fgfr1 mRNA levels were increased in the hypothalamus of diet-induced obese (DIO) rats, showing that FGFR1 is a novel human obesity candidate gene that may affect metabolism and control of food intake." (PMID 25427253, 2014).
lymphoma (27 papers, 2002 to 2025). A malignant (clonal) proliferation of B- lymphocytes or T- lymphocytes which involves the lymph nodes, bone marrow and/or extranodal sites. "While FGFR2 alterations and FGFR2 fusion proteins have been identified as drivers of intrahepatic cholangiocarcinoma, FGFR1 fusion proteins are implicated as drivers of stem cell leukemia/lymphoma." (PMID 35574218, 2022). "FGFR1 mutations in lymphoma using regorafenib or pazopanib hydrochloride." (PMID 29507702, 2018). "In myeloid and lymphoid leukemias/lymphomas resulting from constitutive activation of FGFR1 kinases, resistance has been shown to be due either to mutations in FGFR1 or deletions of PTEN." (PMID 33082322, 2020). "Hematologic malignancies are associated with FGFR1 abnormalities present in acute myeloid leukemia (AML), lymphoblastic leukemia/lymphoma and mixed phenotype acute leukemia." (PMID 29649138, 2018). "There was also a borderline correlation between FGFR-1 expression and bulky disease (P=0.07), with 39% of the patients with lymphomas that expressed FGFR-1 having bulky disease compared to 12.5% of patients with lymphomas who did not." (PMID 12087465, 2002). "The lymphoma specimens demonstrated positive staining for basic fibroblast growth factor (in 23%) and fibroblast growth factor receptor-1 (in 58.5%)." (PMID 12087465, 2002). "A borderline correlation was noted between the expression of bFGF and its receptor (P=0.067): 87.5% of the patients who expressed bFGF in their lymphomas, also expressed FGFR-1, compared to only 50% of the patients who's lymphomas did not express bFGF." (PMID 12087465, 2002). "Staining of lymphoma specimens for bFGF receptor (FGFR-1) was performed in 41 patients." (PMID 12087465, 2002). "For instance, in the Eu-myc + lymphoma mouse model, the secretion of fibroblast growth factor-4 (FGF4) by lymphoma cells and its binding to the cognate receptor FGFR1 on endothelial cells prompts Notch ligand Jagged1 (Jag1) expression by these cells." (PMID 34395425, 2021). "For example, ZMYM2::FGFR1 most commonly presents as a T-lymphoblastic leukemia/lymphoma, BCR::FGFR1 and TPR::FGFR1 present histologically similar to chronic myeloid leukemia (CML), and CEP43::FGFR1 and CNTRL::FGFR1 show features similar to chronic myelomonocytic leukemia (CMML)." (PMID 38611061, 2024). "Eleven of the 17 patients with lymphomas with negative staining for FGFR-1 (64.7%) achieved complete remission compared to only eight of the 24 patients with lymphomas with positive staining (33.3%)." (PMID 12087465, 2002). "Furthermore, FGFR1 inhibition has shown efficacy in pre-clinical in vitro and in vivo MCL models, suggesting that FGFR1 may become a therapeutic target in this type of lymphoma, even without evidence of overt transdifferentiation." (PMID 38638855, 2024).
sarcoma (25 papers, 2013 to 2026). A usually aggressive malignant neoplasm of the soft tissue or bone. "Triggered by an FGFR1-rearranged unclassified high-grade sarcoma with myogenic differentiation, we investigated our molecular database for sarcomas with FGFR gene fusions to assess their recurrent potential and morphologic spectrum." (PMID 42185943, 2026). "The fibroblast growth factor receptor family members,FGFR1-4,are frequently overexpressed in various solid tumors, including breastcancer and sarcomas." (PMID 39989790, 2025). "In pediatric sarcoma databases, the rates of alterations of the FGFR1, FGFR2, FGFR3, and FGFR4 genes were 1.3%, 0.2%, 0.2%, and 2.4%, respectively, while in neuroblastoma tumor samples, the rates of alterations were 0.2% for each." (PMID 40510032, 2025). "On the other hand, the FGFR1-fusion sarcomas show high mitotic activity in 10 HPF, moderate–diffuse lymphoplasmacytic infiltration, and native gland entrapment." (PMID 39064514, 2024). "Mechanistically, we found that this novel intronic circFGFR1int2 promoted FGFR1 expression by recruiting the transcription activators P65 (RELA) and FUS (fused in sarcoma), and by suppressing miR-4687-5p, which was found to be an inhibitor of FGFR1." (PMID 37993879, 2023). "Recently, an evaluation of FGFR alteration targeting is underway advanced sarcomas harboring pre-specified alterations in FGFR1-4 (ClinicalTrials.gov Identifier:NCT04595747)." (PMID 37888109, 2023). "With regard to FGFR inhibitors specifically used in sarcomas, there is a recent case report of a patient with TIO associated with metastatic PMT in which treatment with infigratinib, a FGFR1-3 TKI, dramatically decreased bone lesions." (PMID 34204560, 2021). "Along the same line, a recent paper using a proteomic strategy identified another protein, Protein Tyrosine Phosphatase Receptor Type G (PTPRG), to be involved in controlling FGFR1 activity and influences sensitivity of sarcoma cells to FGFR kinase inhibitors." (PMID 31137681, 2019). "TOP2A (DNA topoisomerase II alpha) and FGFR1 (fibroblast growth factor receptor 1) were the most frequently upregulated targets across all analyzed sarcoma samples (n=14/20 and n=9/20 biopsies, respectively)." (PMID 29755686, 2018). "This may point to the evolution of a high-grade sarcoma from a H3F3A-negative, but FGFR1-positive subclone with acquisition of additional mutations in AKT2 and NRAS during tumor progression." (PMID 33707617, 2021). "However, the recurrence of the GCTB and the sarcoma revealed an overlapping mutation for FGFR1, which was not present in the first biopsy." (PMID 33707617, 2021). "In a recent large study of sarcoma, CGP identified potentially actionable kinase fusions (including NTRK1‐3, ALK, BRAF, FGFR1‐4, RET, and ROS1) in 2.6% of patients." (PMID 38925616, 2024). "To evaluate the expression of targeted receptors in OS, we performed a pan-cancer analysis of The Cancer Genome Atlas (TCGA) database and found that FGFR1 and CSF1R were highly expressed in sarcomas." (PMID 37361567, 2023). "This included FGFR1 amplification in RMS (n = 3), Ewing sarcoma (ES; n = 2), OS (n = 1) and a sarcoma other (n = 1); FGFR3 amplification in a CNS tumour (n = 1); and FGFR4 amplification in RMS (n = 3)." (PMID 37130917, 2023). "This comprehensive analysis ultimately revealed FGFR1 copy number gain and overexpression in UPS, LMS, and DDLPS as well as other sarcoma subtypes." (PMID 34204560, 2021). "These included ALK, BRAF, FGFR1–4, NTRK1–3, RET, and ROS1 kinase fusions in a wide range of sarcoma histologies, including IMT (62.1%), MPNST (4.9%), UPS of bone (4.3%), extraskeletal osteosarcomas (4%), UPS (3.6%), sarcoma NOS (3.8%), and LMS (1.9%)." (PMID 35705558, 2022). "Interestingly in U2OS sarcoma cells, PTPRG directly dephosphorylates the active FGFR1, connecting for the first time PTPRG to the development of sarcomas." (PMID 35071225, 2021).
sarcoma (continued). "We tested the effect of siRNA-mediated SNF5-knockdown in a panel of non-MRT sarcoma cell lines with low or moderate FGFR1 and FGFR2 levels, as well as in BJ cells, a non-immortalized human fibroblast line, previously reported to have a functional SWI/SNF complex." (PMID 24204904, 2013). "In addition, by means of qRT-PCR we confirmed the elevated levels of FGFR1 or FGFR2 transcript in the MRT cells in comparison to two non-FGFR-dependent sarcoma lines, SK-LMS1 and SK-UT-1." (PMID 24204904, 2013). "Importantly, both the high-grade sarcoma and the TCGA cohorts showed that FGFR1 mRNA overexpression could also occur in the absence of FGFR1 copy number alterations." (PMID 34204560, 2021).
pilocytic astrocytoma (24 papers, 2015 to 2025). Pilocytic astrocytoma is a rare subtype of low-grade glioma of the central nervous system characterized by a well circumscribed, often cystic, brain tumor with a discrete mural nodule and long, hair-like projections that extend from the neoplastic astrocytes. "In another patient with ECCL and a pilocytic astrocytoma, the authors identified a N546K mutation in FGFR-1 which showed a differential distribution across all samples including those unaffected tissues." (PMID 41283481, 2025). "FGFR1 hotspot mutations, including N546 and K656, are commonly observed in pilocytic astrocytoma and DNT." (PMID 41323387, 2025). "For example, FGFR1 mutation or rearrangement has been described in pilocytic astrocytoma, diffuse astrocytoma, and dysembryoplastic neuroepithelial tumor (DNT)." (PMID 41323387, 2025). "Again this data is in agreement with the suggested frequency of 5% FGFR1 mutations in pilocytic astrocytoma." (PMID 35018490, 2022). "The FGFR1 mutations were observed only in tumors diagnosed as pilocytic astrocytoma, dysembryoblastic neuroepithelial tumors and rosette-forming glioneuronal tumor." (PMID 35018490, 2022). "FGFR1 mutations most frequently (20%) accompany DNTs, other glioneuronal tumors, and tumors in midline brain structures, but they rarely occur in pilocytic astrocytomas and oligodendrogliomas." (PMID 34572171, 2021). "These two residues are the most commonly mutated residues in FGFR1 in human cancers and interestingly are described predominately in CNS tumors, mostly histologic pilocytic astrocytomas." (PMID 32085805, 2020). "In fact, in some early studies, FGFR1 mutation in pilocytic astrocytoma was associated with a significantly poorer prognosis, although sample size was small." (PMID 32085805, 2020). "Most recently, frequent FGFR1 mutations in two hotspot sites were revealed in another brain tumor: pilocytic astrocytoma." (PMID 29159601, 2018). "The recurrently altered genes also included FGFR1, in which activating point mutations were recently discovered in pediatric pilocytic astrocytoma." (PMID 29159601, 2018). "FGFR1 mutation in the tyrosine kinase domain, which has been reported in pilocytic astrocytomas, diffuse brainstem gliomas, and thalamic gliomas, was identified in two DCGs (DCG_11 and _15)." (PMID 28852847, 2017). "However, given the presence of a solitary FGFR1 mutation and the circumscribed nature of the relapsed tumor, our suspicion points toward a pilocytic astrocytoma for the primary tumor." (PMID 41323387, 2025). "Moreover, FGFR1 is frequently mutated in multiple low‐grade neuroepithelial tumors including pilocytic astrocytoma, and patients with ECCL display an increased risk of pilocytic astrocytomas." (PMID 35778969, 2022). "However, FGFR1 mutations have also been reported in pilocytic astrocytoma, oligodendroglioma, and other histologies, and therefore are not histologically restricted." (PMID 32164789, 2020). "Another patient with a pilocytic astrocytoma had a confirmed FGFR1 mutation." (PMID 33063010, 2020). "Histologic examination showed pilocytic astrocytoma (PA) with anaplasia, and molecular characterization revealed FGFR1 duplication with additional variants of unknown significance in several genes (ARID1A, ARID1B, CHEK2, EPHA5, and MLL2)." (PMID 29610389, 2018). "FGFR1 mutation harboring p.K656E, whose biological effect in promoting tumor growth has been demonstrated, has been reported in pediatric diffuse midline glioma H3 K27M-mutant and pilocytic astrocytomas." (PMID 28852847, 2017). "A pilocytic astrocytoma with high-grade progression designation was considered, given the combination of MAPK pathway alteration (FGFR1 hotspot mutation) and ATRX loss in the high-grade areas." (PMID 39335555, 2024).